MAG (myelin associated glycoprotein)
Description:
Adhesion molecule that mediates interactions between myelinating cells and neurons by binding to neuronal sialic acid-containing gangliosides and to the glycoproteins RTN4R and RTN4RL2 (By similarity). Not required for initial myelination, but seems to play a role in the maintenance of normal axon myelination. Protects motoneurons against apoptosis, also after injury; protection against apoptosis is probably mediated via interaction with neuronal RTN4R and RTN4RL2. Required to prevent degeneration of myelinated axons in adults; this probably depends on binding to gangliosides on the axon cell membrane (By similarity). Negative regulator of neurite outgrowth; in dorsal root ganglion neurons the inhibition is mediated primarily via binding to neuronal RTN4R or RTN4RL2 and to a lesser degree via binding to neuronal gangliosides. In cerebellar granule cells the inhibition is mediated primarily via binding to neuronal gangliosides. In sensory neurons, inhibition of neurite extension depends only partially on RTN4R, RTN4RL2 and gangliosides. Inhibits axon longitudinal growth (By similarity). Inhibits axon outgrowth by binding to RTN4R (By similarity). Preferentially binds to alpha-2,3-linked sialic acid. Binds ganglioside Gt1b (By similarity).
Synonyms: GMA; SIGLEC4A; SIGLEC-4A; S-MAG; SIGLEC4; SPG75
Tractability: Antibody: a drug acting on it is in phase 2 or 3 trials; UniProt places it where antibodies can reach, with high confidence; its Gene Ontology location is reachable by antibodies, with high confidence; UniProt predicts a signal peptide or a membrane-spanning region. PROTAC: UniProt records ubiquitination sites on it; a small molecule that binds it is known.
Target class: Adhesion
Gene: Protein-coding gene on chromosome 19 (35,291,647 to 35,316,351, forward strand). Ensembl gene ENSG00000105695.
Subcellular location: Cell membrane; Membrane raft
Subcellular location (Human Protein Atlas): Equatorial segment; Perinuclear theca
Pathways (Reactome):
Developmental Biology: EGR2 and SOX10-mediated initiation of Schwann cell myelination
Hemostasis: Basigin interactions
Signal Transduction: Axonal growth inhibition (RHOA activation)
Gene Ontology:
Molecular function: protein binding; ganglioside GT1b binding; sialic acid binding; protein homodimerization activity; protein kinase binding; signaling receptor binding
Biological process: cell adhesion; cell-cell adhesion; negative regulation of axon extension; negative regulation of neuron apoptotic process; negative regulation of neuron projection development; cellular response to mechanical stimulus; central nervous system myelin formation; central nervous system myelination; myelination; negative regulation of neuron differentiation; nervous system development; positive regulation of astrocyte differentiation; positive regulation of myelination
Cellular component: compact myelin; myelin sheath; plasma membrane; membrane raft; mesaxon; myelin sheath adaxonal region; paranode region of axon; Schmidt-Lanterman incisure
Genetic constraint (gnomAD): Loss-of-function variants: 30 observed, 55.41 expected, observed/expected ratio (o/e) 0.54, 90% interval 0.4 to 0.73. The upper end of that interval is the gene's LOEUF score, 0.73, which puts it in group 3 of 6, group 1 being the genes least tolerant of losing a copy. Missense variants: 795 observed, 840.46 expected, observed/expected ratio (o/e) 0.95, 90% interval 0.89 to 1. Synonymous variants: 384 observed, 369.09 expected, observed/expected ratio (o/e) 1.04, 90% interval 0.96 to 1.13.
Gene-disease validity (ClinGen):
ClinGen rates the evidence that MAG causes each of these diseases.
complex hereditary spastic paraplegia (autosomal recessive): Definitive. A hereditary spastic paraplegia that is part of a larger syndrome.
Homologues: Orthologues: chimpanzee MAG (99% identical), pig MAG (96% identical), rat Mag (95% identical), mouse Mag (94% identical), guinea pig MAG (89% identical), tropical clawed frog mag (52% identical), zebrafish mag (39% identical). Paralogues in human: SIGLEC5 (20% identical), SIGLEC1 (19% identical), SIGLEC10 (18% identical), SIGLEC9 (17% identical), SIGLEC11 (17% identical), SIGLEC8 (16% identical), SIGLEC7 (16% identical), SIGLEC12 (15% identical), SIGLEC14 (15% identical), SIGLEC6 (15% identical), CD22 (13% identical), CD33 (13% identical), and 4 more.
Diseases named in the same sentence as MAG in open-access papers:
MAG is named in the same sentence as 156 diseases in open-access papers, as found by Europe PMC text mining. Sharing a sentence is not in itself a finding about the gene and the disease. The quoted sentences say what the papers report.
neuropathy (105 papers, 2009 to 2026). A disorder affecting the nervous system that manifests with pain, tingling, numbness, and/or muscle weakness. "A parallel evaluation for alternative neuropathy causes (e.g., anti-MAG antibodies, diabetes, and vitamin B12 deficiency) is also advised." (PMID 41154413, 2025). "Here, we describe the clinical course and treatment outcomes of a patient with anti-MAG antibody neuropathy associated with WM, who was prescribed zanubrutinib after experiencing suboptimal response to rituximab." (PMID 40351903, 2025). "Future research is needed to clarify the boundaries between these two neuropathies, ideally through the development of more precise diagnostic tools or criteria that guide testing for anti-MAG antibodies only in appropriate clinical contexts." (PMID 40748018, 2025). "This is because the presence of anti-MAG antibodies is associated with neuropathy-associated IgM monoclonal gammopathy, suggesting that MAG molecules serve as accessible antigens located on the membrane surface." (PMID 40076855, 2025). "Serum antibodies of anti-MAG neuropathy patients interactwith HNK-1 epitopes that have been found on N-linkedglycoproteins such as myelin associated glycoprotein (MAG) and myelinproteins (P0, P22) and NCAM and as part of glycosphingolipids." (PMID 40627147, 2025). "In contrast, elevated anti-MAG IgM titers in serum are predominantly associated with the distinct peripheral demyelinating disorder anti-MAG neuropathy, making a direct pathological relevance of anti-MAG antibodies in MS improbable." (PMID 41226806, 2025). "Approximately 5% of patients with WM will experience neuropathy in reaction to anti-myelin-associated glycoprotein (anti-MAG) antibodies." (PMID 40351903, 2025). "Myelin-associated glycoprotein (MAG) antibody-positive neuropathy was diagnosed based on the results of serum MAG antibody testing and nerve biopsies." (PMID 39742167, 2024). "Monoclonal IgM can also cause autoimmune phenomena according to its antigenic target, resulting in complement-mediated destruction, such cold agglutinin syndrome (CAS) and anti-myelin-associated-glycoprotein (MAG) neuropathy." (PMID 39558954, 2024). "In our cases, M-proteinemia was thought to be caused by DLBCL in case one and MAG antibody-positive neuropathy in case two." (PMID 39742167, 2024). "Anti-MAG neuropathy is a type of paraproteinemic neuropathy characterized by the presence of autoantibodies against myelin-associated glycoprotein (MAG), a structural myelin protein found in both the peripheral and central nervous systems." (PMID 39766493, 2024). "Biallelic RFC1 mutations were found in three patients with immune-mediated neuropathies, including Guillain-Barré syndrome, idiopathic sensory ataxic neuropathy, or anti-myelin-associated glycoprotein (MAG) neuropathy, who responded to immunotherapies." (PMID 37853169, 2023). "Antibody reactivity was determined in sera from 95 patients with clinical and neurophysiological evidence of anti-MAG-associated neuropathy and in control samples from 55 patients with other forms of peripheral neuropathy." (PMID 38169815, 2023). "Anti-myelin-associated glycoprotein (MAG) antibody is found in nearly half of MGUS patients with neuropathy." (PMID 37108447, 2023). "We analyzed 95 patients (F = 32, median age 74 years, range 49–92) with clinical and neurophysiological signs compatible with anti-MAG-associated neuropathy confirmed using the recommended ELISA (>1,000 BTU)." (PMID 38169815, 2023). "Recently, Doneddu and colleagues developed a diagnostic score for differentiating anti-MAG neuropathy from CIDP-MAG." (PMID 36672019, 2022). "Preliminary positive data on the BTK inhibitor, ibrutinib, in patients with anti-MAG antibody neuropathy and a specific mutational profile (MYD88L265P mutation, wild-type CXCR4 gene) need further confirmation on larger populations." (PMID 35349079, 2022).
neuropathy (continued). "Recently we reported on the first 3 patients with anti-MAG antibody neuropathy and WM (MYD88L265P mutation and wild-type CXCR4 gene), treated with ibrutinib." (PMID 35349079, 2022). "IgM monoclonal gammopathy against MAG in fringe nerves causes myelin-associated glycoprotein (MAG) neuropathy." (PMID 36046684, 2022). "Given the complexity and variety of IgM associated neuropathies, a detailed history, complete neurological examination, nerve conduction studies and serologic evaluation for antibodies against MAG or gangliosides are key to reaching an accurate diagnosis." (PMID 35756635, 2022). "Similar polymorphism changes have also been reported in anti-myelin-associated glycoprotein (MAG) neuropathy and rheumatoid arthritis." (PMID 36503481, 2022). "Anti-myelin-associated glycoprotein (MAG) neuropathy is a rare disease with a prevalence of approximately 1 in 100,000, although representing the most common paraproteinemic neuropathy, which predominantly affects elderly males." (PMID 36672019, 2022). "The neuropathy was first described by Latov in 1980 as a neuropathy caused by an IgM monoclonal peak reacting against peripheral nerve myelin, with MAG later identified as the molecular target." (PMID 33498362, 2021). "Anti-myelin-associated glycoprotein (anti-MAG) neuropathy is a chronic demyelinating sensorimotor polyneuropathy associated with IgM monoclonal gammopathy and is the most common paraproteinemic neuropathy." (PMID 33498362, 2021). "In this study, we report a novel homozygous missense variant in MAG (c.124T>C; p.Cys42Arg) in a Portuguese family with early-onset autosomal recessive ataxia with neuropathy and oculomotor apraxia, identified by exome sequencing." (PMID 32340215, 2020). "In this study, we identified a novel homozygous missense variant in MAG (c.124T>C; p.Cys42Arg) in a Portuguese family with early-onset autosomal recessive cerebellar ataxia with neuropathy and oculomotor apraxia." (PMID 32340215, 2020). "For example, polyneuropathy of POEMS syndrome, monoclonal gammopathy and anti-myelin associated glycoprotein neuropathy exhibited uncompacted myelin lamellae either inside or outer part of the myelin sheath." (PMID 31884566, 2020). "The treatment strategy in anti-MAG associated neuropathies is limited due to the low response rate to current therapies." (PMID 30992531, 2019). "Anti-myelin associated glycoprotein antibody (anti-MAG) neuropathy is a type of immune-mediated neuropathy." (PMID 31249636, 2019). "Immunostaining reactivity was indistinguishable from patients with monoclonal gammopathy associated anti-MAG neuropathy and different from patients with anti-sulfatide antibody- associated neuropathy." (PMID 30992531, 2019). "For example, we generated the di-glycan D221N/C309L/N297A/C575A mutant that displayed marked binding to Siglec-1 and Siglec-4 (MAG), both receptors being clinically implicated in the control of neuropathy." (PMID 30683699, 2019). "This has, however, been associated with anti- myelin-associated glycoprotein (MAG)-associated neuropathy and the worsening was noted to be transient and reversible after several weeks to months." (PMID 31878962, 2019). "Anti-Myelin Associated Glycoprotein (MAG) neuropathy is a demyelinating polyneuropathy associated with IgM monoclonal gammopathy towards MAG in peripheral nerves." (PMID 30941082, 2019). "Antibodies against myelin-associated glycoprotein (MAG) almost invariably appear in the context of an IgM monoclonal gammopathy associated neuropathy." (PMID 30992531, 2019). "In nerve from patients with WM, pathological findings are similar to those seen in the neuropathy associated with anti-MAG." (PMID 30264176, 2019). "M-protein is present in 10% of cryptogenic neuropathies, mostly IgM, and in 50% of the IgM cases the M-protein has an anti-myelin associated glycoprotein (anti-MAG) activity." (PMID 29849629, 2018).
neuropathy (continued). "Although anti-myelin-associated glycoprotein (MAG) antibody neuropathy is reported as a slowly progressive disease, it can lead to significant disability and impairment of health-related quality of life (HR-QoL) and social participation." (PMID 30306264, 2018). "One such example of a therapeutic application can be found in a recent novel approach to treating anti-myelin-associated glycoprotein (anti-MAG) neuropathy, a rare, disabling autoimmune disorder." (PMID 29259668, 2017). "The use of a multivalent glycopolymer mimicking the natural HNK-1 epitope proved to be a valid approach to selectively sequester the autoantibodies associated with anti-MAG neuropathy onset." (PMID 29259668, 2017). "Improvement in anti-MAG–associated neuropathy has been reported with plasma exchange, chlorambucil (Leukeran), fludarabine, and rituximab (Rituxan; Blade & Rosinol, 2007)." (PMID 25031979, 2013). "Here, we report a case of myelin-associated glycoprotein-related neuropathy associated with psoriasis." (PMID 23286283, 2013). "Although both of these diseases are considered autoimmune diseases, psoriasis with concomitant myelin-associated glycoprotein-related neuropathy is very rare." (PMID 23286283, 2013). "Almost half of the patients with an IgM M-protein and neuropathy will have elevated titers of antibodies against myelin-associated-glycoprotein (MAG)." (PMID 22379454, 2011). "Typically, anti-MAG antibody-associated neuropathy presents as an insidious, distal, predominantly sensory neuropathy with some distal weakness." (PMID 22379454, 2011). "An extensive workup revealed anti-myelin-associated glycoprotein neuropathy as the only presenting feature of low grade B cell Lymphoma." (PMID 19829796, 2009). "Additionally, novel agents such as Bruton's tyrosine kinase inhibitors (BTKis) are gaining attention, particularly in cases of anti-MAG neuropathy associated with Waldenström macroglobulinemia, supported by preliminary evidence of efficacy." (PMID 41031196, 2025). "Our findings also provide insights to better understand certain cases of acquired demyelinating disorders of peripheral nerves (e.g., Guillain-Barré syndrome, anti–myelin-associated glycoprotein neuropathy) as well as nerve injury and remyelination, where lipids are considered limiting resources." (PMID 40338666, 2025). "IgM‐associated neuropathy can be related to anti‐myelin‐associated glycoprotein (MAG) antibodies." (PMID 38840755, 2024). "Interleukin‐6 (IL‐6) could be a target of future research with regards to VTE risk in patients with anti‐MAG neuropathy, as they have higher median IL‐6 levels than healthy controls." (PMID 38015467, 2024). "The fascicle CSA appears to be more increased in CIDP and its variant than in anti-MAG neuropathy." (PMID 38409319, 2024). "Furthermore, these IgM molecules can infiltrate the peripheral nervous system and lead to a variety of neurological complications, such as amyloid-induced neuropathy or anti-myelin-associated glycoprotein (anti-MAG) neuropathy." (PMID 39417016, 2024). "Our study raises the important question of whether the multiple myeloma VTE risk stratification algorithm is adequate for anti‐MAG neuropathy." (PMID 38015467, 2024). "There is good evidence that the anti-MAG antibodies cause neuropathy." (PMID 38325389, 2024). "Furthermore, a recent study identified a grey area between 1,500 and 7,000 BTU in which the differential diagnosis between chronic inflammatory demyelinating polyneuropathy (CIDP) and anti-MAG-associated neuropathy is challenging." (PMID 38169815, 2023). "This detachment may be the primary cause of axonal damage and subsequent axonal loss in anti-MAG neuropathy." (PMID 36672019, 2022). "The differential diagnoses to keep in mind are chronic inflammatory polyradiculoneuropathy (CIPD), anti-myelin-associated-glycoprotein (MAG) neuropathy, monoclonal gammopathy of undetermined significance (MGUS), and immunoglobulin light chain (AL) amyloid neuropathy." (PMID 36498588, 2022).